FCN3 (ficolin 3)
Diseases named in the same sentence as FCN3 in open-access papers (continued):
Sharing a sentence is not in itself a finding about the gene and the disease.
systemic lupus erythematosus (6 papers, 2016 to 2023). An autoimmune multi-organ disease typically associated with vasculopathy and autoantibody production. "On the other hand, high ficolin-3 levels were associated with Systemic Lupus Erythematosus, ovarian tumors and seem to be a risk factor for shorter graft survival in kidney transplantation." (PMID 28241035, 2017). "Although a causal relationship between the presence of anti-ficolin-3 antibodies and lupus nephritis remains to be determined, the possible role of anti-ficolin-3 antibodies in the pathogenesis of lupus is a key issue." (PMID 27631981, 2016). "The mutation or deficiency of FCN3 may cause immune disorders like SLE (Systemic Lupus Erythematosus)." (PMID 33043022, 2020). "Indeed, only one previous study reported the presence of auto-antibodies against ficolin-3 in lupus sera, but authors used a double immunodiffusion technique which was not quantitative." (PMID 27631981, 2016).
type 2 diabetes (6 papers, 2013 to 2024). "Ficolin-3 has been associated with metabolic diseases including gestational, prediabetes, and type 2 diabetes, and identified as biomarkers in axial spondyloarthritis and as a prognostic biomarker for esophageal cancer." (PMID 32411128, 2020). "Additionally, low ficolin-3 was independently associated with IR and predicted type 2 diabetes mellitus (T2DM)." (PMID 39635529, 2024). "Our data suggest that ficolin-3-mediated lectin and alternative pathway activations may have an impact on the clinical outcome of patients with type 2 diabetes having bacterial infections." (PMID 30949171, 2019). "Moreover, ficolin-3 has been shown to be decreased in patients with diabetic nephropathy, and that it varied significantly between type 2 diabetes patients and controls." (PMID 23596511, 2013). "Based on previous IR research, this relationship was as expected because a reduction in ficolin-3, a protein structurally and functionally similar to FCN2, has previously been identified as a biomarker of type 2 diabetes." (PMID 28441961, 2017). "In our prospective study, we found decreased in vivo activation of ficolin-3-mediated lectin and alternative pathways during bacterial infections in patients with type 2 diabetes in comparison with non-diabetic subjects." (PMID 30949171, 2019).
Immunodeficiency (5 papers, 2010 to 2024). Failure of the immune system to protect the body adequately from infection, due to the absence or insufficiency of some component process or substance. "We have recently described a patient with a history of severe recurrent infections that was homozygous for the FCN3+1637delC mutation and had no detectable Ficolin-3 in serum, suggesting that complete lack of Ficolin-3 is a novel immunodeficiency associated with disease." (PMID 21085669, 2010).
ischemic stroke (5 papers, 2011 to 2021). A stroke disorder caused by obstruction of blood flow to the brain, due to thrombotic (local blood clot formation) or embolic (due to a blood clot or other material traveling from another site) event. "Lower serum ficolin-3 levels have been demonstrated to be highly associated with unfavorable outcome after ischemic stroke." (PMID 26627059, 2015). "Recently, our group reported that concentrations of ficolin-3 were significantly decreased in both the admission and in the follow-up samples of patients with definite ischemic stroke as compared to healthy subjects." (PMID 23596511, 2013). "An inverse correlation was observed between low ficolin-3 levels and high concentration of S100beta, an indicator of the size of cerebral infarct suggesting that ficolin-3 contributes to the pathogenesis of ischemic stroke." (PMID 23596511, 2013). "Concentrations of both ficolin-2 and ficolin-3 were significantly (p < 0.001) decreased in both the admission and in the follow-up samples of patients with definite ischemic stroke as compared to healthy subjects." (PMID 22206485, 2011). "In ischemic stroke, the decreased serum concentration of ficolin-3 could be observed in the very early phase and remained unchanged during the next 3–4 days." (PMID 26627059, 2015). "Therefore, we measured the levels of ficolin-2 and ficolin-3 in sera from 65 patients with ischemic stroke and from controls." (PMID 22206485, 2011). "In addition, ficolin-3 levels inversely correlated with the indirect measure of the severity of ischemic stroke, i.e. with the NIHSS neurological deficit score." (PMID 22206485, 2011). "This association is most probably secondary to the negative correlation between ficolin-3 on the one hand and the severity of ischemic stroke and the infarct size on the other hand." (PMID 22206485, 2011).
rheumatic heart disease (5 papers, 2021 to 2025). An autoinflammatory condition following an infection with Group A Beta Hemolytic Streptococcus (GABHS), in which the heart is attacked by antibodies formed in reaction to a recent GABHS infection. "FCN3, ficolin 3, was the most effective activator of the lectin pathway of complement and more focus in rheumatic heart disease." (PMID 36712235, 2022). "Previous work has indicated this protein may play a role in the pathogenesis of rheumatic heart disease (RHD), and it has been hypothesised that ficolin-3 has potential as a biomarker for early identification of patients with suspected RHD." (PMID 40340734, 2025).
esophageal cancer (4 papers, 2020 to 2022). A primary or metastatic malignant neoplasm involving the esophagus. "LUAD and LIHC patients with low expression of FCN3 have poor prognosis, which is consistent with the findings in liver cancer and esophageal cancer." (PMID 33195408, 2020). "Ficolin 3 (FCN3, 2.7-fold up in aGC) was already suggested as a potential prognostic serum biomarker in esophageal cancer." (PMID 35566209, 2022).
lung adenocarcinoma (4 papers, 2021 to 2024). A carcinoma that arises from the lung and is characterized by the presence of malignant glandular epithelial cells. "In this study, we report a novel function of FCN3 (Ficolin 3), a secreted lectin capable of activating the complement pathway, as a tumor suppressor of lung adenocarcinoma (LUAD)." (PMID 33859174, 2021).
lung carcinoma (4 papers, 2020 to 2025). "FCN3 expression was significantly down-regulated in lung cancer tissues compared with matched normal lung tissues, low expression levels of FCN3 have been described as prognostic biomarker for cancer." (PMID 38683466, 2025). "Our analysis identified four highly significant differentially expressed genes in lung cancer, comprising MIF, CLEC3B, FCN3, and EMCN." (PMID 37359381, 2023). "Our analysis also identified four highly significant differentially expressed genes in lung cancer, namely, MIF, CLEC3B, FCN3, and EMCN." (PMID 37359381, 2023).
Lung Squamous Cell Carcinoma (4 papers, 2013 to 2025). "The FCN3 gene was found to be under-expressed in hepatocellular and squamous cell lung carcinomas." (PMID 23744477, 2013). "At least five out of 12 types of cancer examined including breast invasive carcinoma (BRCA), kidney renal papillary cell carcinoma (KIRP), liver hepatocellular carcinoma (LIHC), lung squamous cell carcinoma (LUSC) and LUAD show significant down-regulation of FCN3 in tumor tissues." (PMID 33859174, 2021).
rheumatoid arthritis (4 papers, 2014 to 2025). A chronic, systemic autoimmune disorder characterized by inflammation in the synovial membranes and articular surfaces. "A systematic literature review was performed using the following keywords “gene (FCN1/FCN2/FCN3)”, “Polymorphism/Genetic Variant”, and “rheumatoid arthritis” in different databases until January 2022." (PMID 36569030, 2022). "The present systematic review was conducted to synthesize the results of the studies in order to establish the impact of polymorphisms in the ficolin-coding genes FCN1, FCN2, and FCN3 on the susceptibility to develop rheumatoid arthritis." (PMID 36569030, 2022). "Ficolin 3, Haptoglobin, Alpha-1-antitrypsin, Hemopexin precursor and IgM chain also showed increased expression in plasma of rheumatoid arthritis patients as an indication of immune response." (PMID 25350754, 2014). "Both polymorphisms in the FCN1 gene (rs2989727 and rs1071583), but not in FCN2 and FCN3, are associated with the risk of developing rheumatoid arthritis in populations from Brazil and Belgium." (PMID 36569030, 2022). "The FCN1 gene variants, particularly rs2989727 and rs1071583, have been reported to be linked to increased risk of developing rheumatoid arthritis in Brazilian and Belgian populations, whereas no such associations were observed for FCN2 or FCN3 variants." (PMID 41285030, 2025). "The FCN1 gene variants rs2989727 and rs1071583 are associated with the risk of developing rheumatoid arthritis in populations from Brazil and Belgium, but not in FCN2 and FCN3 gene variants." (PMID 36569030, 2022). "No anti-ficolin-3 antibodies were found in patients with rheumatoid arthritis (n = 14), Sjögren’s syndrome (n = 12), chronic renal failure (n = 12) and IgA nephropathy such as Berger disease (n = 12)." (PMID 27631981, 2016).
bacteremia (3 papers, 2016 to 2020). "Low ficolin-3 concentration was however suggested to be a risk factor for febrile neutropenia (especially with bacteremia) in pediatric cancer patients treated with chemotherapy." (PMID 32047495, 2019).
cerebral infarct (3 papers, 2011 to 2015). "According to our second observation, lower level of ficolin-3 in the follow-up samples were associated with greater size of the cerebral infarct indicated by higher S100β levels in the sera." (PMID 22206485, 2011). "In follow-up samples an inverse correlation was observed between ficolin-3 levels and concentration of S100β, an indicator of the size of cerebral infarct." (PMID 22206485, 2011).
Insulin resistance (3 papers, 2018 to 2024). Increased resistance towards insulin, that is, diminished effectiveness of insulin in reducing blood glucose levels. "However, some studies suggest that low serum levels of FCN3 are associated with insulin resistance and diabetic peripheral neuropathy." (PMID 38375199, 2024).
liver cancer (3 papers, 2020 to 2024). An epithelial or non-epithelial malignant neoplasm that arises from the liver. "The results showed that UBE2C, PTTG1, TOP2A and SPP1 were positive, FCN3, SLC22A1, ADH4, CYP2C8, SLC10A1, and FBP1 were negative in liver cancer tissues." (PMID 38664521, 2024).
preeclampsia (3 papers, 2013 to 2025). Preeclampsia is a hypertensive disorder of pregnancy that is characterized by new-onset hypertension with proteinuria presenting after 20 weeks of gestation, and depending on mild or severe forms may initially present with severe headache, visual disturbances, and hyperreflexia. "A study investigating the maternal proteome in preeclampsia via LC–MS/MS approaches reported on 17 differentially expressed proteins in the serum, from which our study also identified VWF, PAPPA, FCN3, and ITIH1 as candidates associated with the mode of conception." (PMID 40974471, 2025). "Ficolin-3 appears to be consumed in preeclampsia and binds to apoptotic placentas." (PMID 23596511, 2013).
Sepsis (3 papers, 2021 to 2026). Sepsis is defined as life-threatening organ dysfunction caused by a dysregulated host response to infection. "Very recently, elevated levels of FCN3, together with galectin-3, have also been found in sera of patients with AKI, following complicated sepsis and correlated with the severity of renal damage." (PMID 40427671, 2025).
subarachnoid hemorrhage (3 papers, 2016 to 2022). A serious neurological disorder characterized by intracranial hemorrhage into the subarachnoid space. "The subarachnoid hemorrhage in humans is another example of human pathologic condition associated with ficolin-3-dependent C activation." (PMID 35711467, 2022). "Our own recent work has demonstrated that ficolin-3 drives LP activation in patients with subarachnoid hemorrhage." (PMID 27577570, 2016). "A recent study shows that ficolin-3 functional LP activity, but not its levels, was associated with unfavorable outcome in subarachnoid hemorrhage patients." (PMID 26792363, 2016).
type 1 diabetes (3 papers, 2018 to 2024). "An 18-year follow-up study discovered that elevated levels of FCN3 in circulation were associated with a higher incidence of micro- or macroalbuminuria in patients newly diagnosed with type 1 diabetes." (PMID 38375199, 2024).
aortic aneurysm (2 papers, 2022 to 2023). A ruptured aneurysm located in the wall of the proximal portion of the descending aorta proceeding from the arch of the aorta. "It is known, that in patients affected by aortic aneurysm, platelet-derived EVs carry increased levels of ficolin-3, compared to healthy subjects, and these EVs were associated with aneurysm progression." (PMID 36555653, 2022). "Additionally, ficolin-3 + platelet-derived EVs are well elevated in the plasma of aortic aneurysms patients which contribute to the progression of aneurysms." (PMID 37566042, 2023).
asthma (2 papers, 2023 to 2024). "Although it was not possible to find proteins that could discriminate all the asthma phenotypes in serum, FCN3 is notable, as it could discriminate eosinophilic from the neutrophilic and mixed granulocytic groups." (PMID 38542471, 2024). "Although it was not possible to develop a biomarker panel from serum proteins that could distinguish all the four asthma phenotypes, important proteins could significantly distinguish some phenotypes, as FCN3 was detected in different levels between eosinophilic and neutrophilic asthma." (PMID 38542471, 2024).
autoimmune disease (2 papers, 2022 to 2023). A disorder resulting from loss of function or tissue destruction of an organ or multiple organs, arising from humoral or cellular immune responses of the individual to their own tissue constituents. "Most genes were related to autoimmune diseases like ATM, NCF1, MCM4, FCN3, and DOCK8 or autoinflammatory diseases associated with the release of IFN-gamma, such as PRF1, NOD2, and MEF." (PMID 37588055, 2023).
carotid atherosclerosis (2 papers, 2011 to 2017). A thickening and loss of elasticity of the walls of carotid arteries that occur with formation of atherosclerotic plaques. "Füst and collaborators showed increased ficolin-2 and ficolin-3 serum levels in asymptomatic patients with severe carotid atherosclerosis compared to healthy controls or to patients after acute stroke." (PMID 28360913, 2017).
Cerebral ischemia (2 papers, 2014 to 2015). Restriction of arterial blood supply to the brain associated with insufficient oxygenation to support the metabolic requirements of the tissue. "Moreover, low levels of plasma ficolin-3 were related to severity, vasospasm, and cerebral ischemia of aneurysmal subarachnoid hemorrhage." (PMID 26627059, 2015).
congenital heart disease (2 papers, 2016 to 2022). A heart disease that is present at birth. "In congenital heart disease, the protein of FCN3 may prolong bleeding time and increase susceptibility to lung infection in the Fallot." (PMID 36712235, 2022). "Interestingly, homozygosity for FCN3 + 1637delC accompanied with the AX/D genotype was recently confirmed in an 11-month-old infant with congenital heart disease, pneumonia (without recurrence) and no severe infections after cardiac surgery." (PMID 26795763, 2016).
Hypertension (2 papers, 2024 to 2025). The presence of chronic increased pressure in the systemic arterial system. "Ficolin-3 (FCN3), a principal molecule in this pathway, is pivotal for the activation of complement component 3 and has been linked to hypertension risk." (PMID 39717447, 2024).
injury (2 papers, 2015 to 2023). Damage inflicted on the body as the direct or indirect result of an external force, with or without disruption of structural continuity. "Compared with the healthy controls, serum ficolin-3 levels on admission were statistically decreased in patients with severe traumatic brain injury." (PMID 26627059, 2015). "It was proposed that lower serum ficolin-3 levels, correlated with injury severity, had the potential to be the useful, complementary tool to predict short- or long-term clinical outcomes after severe traumatic brain injury." (PMID 26627059, 2015). "Thus, the increased consumption of ficolin-3 might exacerbate complement activation, leading to the inflammation and tissue damage after head trauma." (PMID 26627059, 2015). "Therefore, it is suggested that serum ficolin-3 may have the potential to be a good prognostic predictive biomarker after head trauma." (PMID 26627059, 2015).
lepromatous leprosy (2 papers, 2017 to 2020). A chronic communicable infection which is a principal or polar form of leprosy. "In this study, we observed that higher ficolin-3 levels were associated with the disease per se and with lepromatous leprosy." (PMID 28241035, 2017). "Nevertheless, some associations were lost after multivariate logistic correction (FCN1*3C2, FCN2*AGAAGC, and FCN2*GGGCAC with lepromatous leprosy/HBV infection and MBL2*HYPA, MBL2*LYQC, FCN2*GGGCAC with non-lepromatous leprosy/HBV infection) or due to low sample size (MASP1*AC_CTG, FCN3*2B2.2A)." (PMID 33643280, 2020).
lupus nephritis (2 papers, 2016 to 2022). Glomerulonephritis in the context of systemic lupus erythematosus. "Among various clinical manifestations presented by our patients, the presence of anti-ficolin-3 antibodies was significantly associated with lupus nephritis (p≤0.001, Chi2 test)." (PMID 27631981, 2016). "Regarding associations with clinical manifestations, the presence of active lupus nephritis was significantly associated with the presence of anti-ficolin-3 antibodies (p≤0.001)." (PMID 27631981, 2016). "Importantly, we found that anti-ficolin-3 antibodies were more closely associated with active lupus nephritis than any other auto-antibodies." (PMID 27631981, 2016). "Even if nephritis assessment based on standard parameters such as proteinuria and creatinine remains essential, the combination of anti-ficolin-3 and anti-C1q antibodies could open new perspectives in evaluation of lupus nephritis." (PMID 27631981, 2016). "Interestingly, in our cohort we observed a very high prevalence (70%) of anti-ficolin-3 antibodies in the subset of SLE patients with lupus nephritis." (PMID 27631981, 2016). "Anti-ficolin-3 antibodies were detected as positive in 25 (69%) of 36 SLE patients with active disease and lupus nephritis." (PMID 27631981, 2016). "Patients with active proliferative lupus nephritis (i.e. Classes III and IV) had significantly more positive anti-ficolin-3 and anti-C1q antibodies than those with non-proliferative lupus nephritis (respectively p = 0.001 and p = 0.006, Fisher’s exact test)." (PMID 27631981, 2016). "Interestingly, titers of anti-ficolin-3 antibodies were significantly higher in this subset of SLE patients with active disease and lupus nephritis than in patients with active disease but without renal involvement (median 102 vs 54 AU, p = 0.0016, Mann-Whitney U-test)." (PMID 27631981, 2016).